IL10 (interleukin 10)
Diseases named in the same sentence as IL10 in open-access papers (continued):
Sharing a sentence is not in itself a finding about the gene and the disease.
tumor (continued). "IL-10 facilitates tumor proliferation in CaP by inhibiting antitumor immune response via its influence on immune cells and by directly affecting CaP cells." (PMID 40507238, 2025). "Our findings are consistent with those of other studies.For example, in tumor-associated B cells, STAT3 promotes CTLA4 expression in a JAK-dependent mechanism, while in Treg cells, STAT3 promotes CTLA4 expression via IL-10." (PMID 40092547, 2025). "Tumor growth factor β (TGF-β), interleukin-10 (IL-10), and prostaglandin E2 are rich in the microenvironment of tumor cells." (PMID 40564171, 2025). "In parallel, hypoxic tumor cells secrete a repertoire of immunosuppressive factors, including transforming growth factor-beta (TGFβ), interleukin-10 (IL-10), and vascular endothelial growth factor (VEGF)." (PMID 40963621, 2025). "STING agonists up‐regulate the production of IL‐35 and IL‐10 in Breg cells, which in turn drives tumour growth." (PMID 41275427, 2025). "Lycopene and anti‐PD‐1 treatment synergistically decrease tumor weight, tumor volume, IL‐4, IL‐10, and PD‐L1 expression." (PMID 40661795, 2025). "IL-6 and IL-10 levels, which are known to promote PCs proliferation, also promote the development of the NK-resistant tumor phenotype by inhibiting their activity." (PMID 40755766, 2025). "Although pro-inflammatory cytokines help in controlling tumor growth, the tumor can avoid immunity with immunosuppressive cytokines like IL-10 and TGF-β, which suppress the immune system." (PMID 40309351, 2025). "The qPCR analysis of total mRNA from tumor tissues revealed significant upregulation of M1 markers Nos2, Il1b, and Il6, along with marked downregulation of M2 markers Mcr1, Arg1, and Il10." (PMID 39908200, 2025). "Conversely, anti-inflammatory cytokines such as IL-4 and IL-10 can suppress immune surveillance while paradoxically supporting tumor progression through immunosuppressive mechanisms." (PMID 41614846, 2025). "Some studies have shown that M2 macrophages support tumor growth and metastasis by secreting a variety of tumor-promoting factors, such as IL-10, TGF-β, and VEGF." (PMID 40165975, 2025). "By inhibiting HDAC6, Vorinostat reduces IL-10 levels, which decreases M2 macrophage polarization and consequently limits tumor growth." (PMID 40330466, 2025). "Tumor-derived cytokines such as IL-10, VEGF, and PGE2 inhibit DC maturation, resulting in accumulation of immature or tolerogenic DCs that fail to effectively prime T cells." (PMID 40821795, 2025). "RT released HMGB1 from tumor cells that induce high TNF-α and low levels of IL-10 secretion from M1-type macrophages that exert drastic anti-tumor activity." (PMID 40141437, 2025). "Hypoxia from rapid tumor growth increases M2 macrophages, elevating IL-10, VEGF, and HIF-1α, promoting metastasis and further macrophage infiltration." (PMID 40079009, 2025). "Hypoxia can reprogram macrophage metabolism, pushing them toward an M2-like, tumor-promoting phenotype due to IL-4 and IL-10 secretions or impairing their survival." (PMID 40698077, 2025). "IL10 is a potent immunosuppressive cytokine with immune-regulatory and angiogenic properties, facilitating tumor cell survival, proliferation, and metastasis by inhibiting antitumor immune responses." (PMID 40312750, 2025). "As tumor suppressor, IL-10 exerts multiple mechanisms and pathways to eradicate tumor cells and enhance antitumor immune surveillance." (PMID 40149345, 2025). "Oncolytic vaccinia viruses express IL-2, IL-10, IL-12, IL-15, IL-21, IL-23, IL-24, and IL-36γ remodel the tumor microenvironment,enhance immune cell infiltration, suppress immunosuppressive elements and promot systemic antitumor immunity." (PMID 40469178, 2025). "Tumor cells often secrete immunosuppressive cytokines like TGF-β and IL-10, which promote immune tolerance and inhibit anti-tumor immunity." (PMID 41235220, 2025). "Their primary function is to release TGF-β and IL–10, which predominantly silence the immune response in the tumor’s proximity." (PMID 40427098, 2025).
tumor (continued). "The polarized M2-like macrophage markers and cytokines such as mannose receptors (CD206), scavenger receptors (CD163), VEGF, and IL-10, exhibit tumor-supporting effects." (PMID 40860188, 2025). "For example, regulatory T cells and myeloid-derived suppressor cells in the tumor immune microenvironment can inhibit NK cell activation despite increased infiltration by releasing transforming growth factor-beta, interleukin-10, and nitric oxide." (PMID 40507294, 2025). "MDSCs promote tumor immune evasion primarily by secreting factors such as IL‐10 and TGF‐β and interacting with T cells and other immune cells, posing a significant challenge in cancer immunotherapy." (PMID 40356222, 2025). "Under the influence of immunosuppressive factors in the TME (such as PGE-2 and IL-10), TAMs lose their ability to present antigens and directly kill tumor cells, fail to effectively activate T/NK cells, and thereby promote tumor progression." (PMID 41048488, 2025). "These cells highly express immunosuppressive markers such as CD39, CTLA‐4, and PD‐1 and produce relatively high amounts of IL‐10, which inhibits antitumor immune responses and promotes tumor growth and metastasis." (PMID 39802636, 2025). "This metabolic shift repolarized TAMs to the M1 phenotype, resulting in a decrease in interleukin (IL)-10 secretion, which enhanced the immune response of anti-tumor CD8+ T cells and increased the sensitivity of TNBC to immune checkpoint blockade therapy." (PMID 41137391, 2025). "IFNγ works synergistically with EBNA2 to induce PD-L1 on EBV+ tumor cells; the immunosuppressive cytokine IL-10 acts as critical pathway in suppressing the host’s antiviral T cell response." (PMID 41516315, 2025). "These TAM related effects coupled with the ability of CRC cells to produce IL-10 through STAT3 signaling promotes tumor growth, invasiveness, and aggressiveness." (PMID 40607405, 2025). "The consistent demonstration of IL-10/IL-6 imbalance in both the peripheral circulation (serum) and tumor microenvironment (RNA-seq) underscores the biological significance of this cytokine axis in DLBCL pathogenesis." (PMID 40881684, 2025). "Bregs are characterized by their expression of immunosuppressive cytokines, such as IL-10, IL-33, and TGFβ, and have been primarily studied in mouse tumor models." (PMID 40356924, 2025). "Th2 cells primarily secrete IL-4, IL-6, and IL-10; IL-4 regulates MDSCs by synthesizing arginase 1 (Arg1) and decomposing l-arginine to induce T-cell apoptosis and tumor immunosuppressive effects." (PMID 41278263, 2025). "The diversity of tumor-associated B cells, as revealed by single-cell RNA sequencing, reflects a spectrum from IFN-γ-activated anti-tumor phenotypes to IL-10+ immunosuppressive profiles." (PMID 41244711, 2025). "The anti-tumor effect of IL-10 depends on CD8+ or CD4+ T cell activity, contrary to some who have suggested that the anti-tumor action of IL-10 is caused by increased NK cell activity." (PMID 40933989, 2025). "In the context of CAR T-cell therapy, Tregs can inhibit therapeutic efficacy by creating an immunosuppressive tumor microenvironment as they produce immunosuppressive cytokines such as IL-10 and TGF-β." (PMID 40004068, 2025). "In GBM, however, tumor-derived cytokines such as IL-10, TGF-β, and VEGF impair DC maturation and function." (PMID 41374979, 2025). "Conversely, in the tumor microenvironment, chronic antigen exposure under Th2 (IL-4/IL-13) and IL-10 signaling drives local IgG4 production, which correlates with poor prognosis in malignancies such as melanoma and cholangiocarcinoma." (PMID 40508133, 2025). "Despite promising findings, resistance to BET-targeted therapies have been observed, particularly in TNBC, where TAMs sustain tumor growth through IL-6/IL-10–driven STAT3/NF-κB signaling." (PMID 41583469, 2025). "The differentiation of Treg cells is triggered by TGF-β, IL-10, and cyclooxygenase-2 by tumor and stromal cells." (PMID 40869156, 2025).
tumor (continued). "Neutrophils with activated non-canonical NF-κB pathways are more likely to produce immunosuppressive cytokines, such as TGF-β and IL-10, which dampen anti-tumor immunity and facilitate immune evasion by the tumor." (PMID 40486614, 2025). "Pro-tumor TANs release IL-10 and TGF-β, form neutrophil extracellular traps (NETs) and produce arginase and ROS, which thereby impede the trafficking and activity of T cells." (PMID 40849659, 2025). "Overall, the top four checkpoint genes associated with KLF4 and correlated with a tumor inhibitory effect in several tumors were C10orf54, CD274, IL10, and TGFB1." (PMID 40299916, 2025). "Tumor-infiltrating B cells can rely on IL-10 and collaborate with Tregs to construct an immunosuppressive microenvironment." (PMID 41219968, 2025). "Treg cells further dampen immunity by expressing CD25 and cytotoxic T lymphocyte protein 4 (CTLA4), releasing cytokines like TGFβ and IL-10, and consuming lipids and glucose, all of which impair tumor-killing T cells." (PMID 40741546, 2025). "Tumor cells employ multiple mechanisms to evade immune surveillance, including the accumulation of immunosuppressive cytokines (e.g., IL-10, TGF-β), impaired cytotoxic function, reduced antigen presentation, and T-cell exhaustion." (PMID 40647407, 2025). "On the other hand, IL-10 can inhibit inflammatory factors that promote tumor development, thereby suppressing tumor-related inflammation, and enhancing the body’s anti-tumor effects." (PMID 39980556, 2025). "Prior research has shown that during tumor immune responses, NF-kB pathway activation stimulates the release of IL-10." (PMID 39856752, 2025). "Cytokines such as TNF-α, TGF-β, IL-6, and IL-10 are pivotal players in these processes, driving inflammation, tumor progression, and immune suppression." (PMID 40933989, 2025). "The optimized LNPs successfully deliver therapeutic proteins such as saporin and interleukin‐10 (IL‐10) to inhibit tumor growth in several animal models." (PMID 40056044, 2025). "Cytokines including IL-6, IL-10, IL-11 and IL-24 can suppress immune effector cells, such as T cells, natural killer cells and dendritic cells, impairing the host’s anti-tumour response while facilitating the immune evasion of GBM cells." (PMID 41301734, 2025). "IL-23 is a cytokine that promotes regulatory T cell proliferation and IL-10 expression, both of which can suppress immune-mediated tumor cell killing." (PMID 40427207, 2025). "In HPV-related HNSCC, TAMs activated by tumor-derived IL-10 mediate CD8+ T cell dysfunction through PD-1/PD-L1 interactions." (PMID 40236700, 2025). "By reducing the production of pro-inflammatory cytokines, such as IFN-γ and TNF-α, IL-10 diminishes the effector functions of CTLs, limiting their ability to control tumor growth." (PMID 40739089, 2025). "In contrast, M2 macrophages promote tumor progression by secreting anti-inflammatory factors like interleukin-10 (IL-10), which not only promote angiogenesis and suppress immune responses but also facilitate EMT." (PMID 40098971, 2025). "Despite these advances, the immunosuppressive nature of the GBM tumor microenvironment and the IL-10- and TGF-β-based immune evasion strategies presents ongoing challenges, which must be overcome for therapeutic efficacy." (PMID 41374974, 2025). "The cytokine and chemokine milieu in primary cutaneous melanoma is one characterized by increased mitogenic cytokines, reduced IFN-γ and increased IL-10 levels, thereby facilitating tumor survival and progression." (PMID 39825956, 2025). "Conventionally, M2-polarized TAMs facilitate tumor immune evasion through IL-10/TGFB1 secretion or ARG1 overexpression." (PMID 40959090, 2025).
tumor (continued). "Tumor cells in patients with EBV-positive DLBCL usually express CD30, and there is high expression of immunosuppressive cytokines (such as IL-10) in their microenvironment, which inhibits the host’s anti-tumor immune response." (PMID 40302035, 2025). "When exploring the linked mechanisms on how sGRP78 confer the resistance, it was found that in high sGRP78 index tumors, there were more IL‐10+/PD‐L1+ B subsets and Tregs infiltration, accompanied by accelerated tumor progression and metastasis." (PMID 40936109, 2025). "IL-1β and IL-6, regulated by JAK/STAT and NF-κB signaling, promote tumor proliferation and immune evasion, while IL-10 and TGF-β drive M2 macrophage polarization and Treg expansion, fostering an immunosuppressive tumor milieu." (PMID 40076502, 2025). "This phenomenon is mediated by various tumor-derived factors, including cytokines (e.g., IL-4, IL-10, TGF-β) and chemokines, which collectively promote M2 polarization of macrophages." (PMID 41019043, 2025). "OSCC cells can produce immunosuppressive cytokines such as transforming growth factor-beta (TGF-β) and interleukin-10 (IL-10), which can, in turn, reduce anti-tumor immunity." (PMID 40227635, 2025). "Nevertheless, IL-10 derived from either tumor or immune cells suppresses immune function by creating an “immunosuppressive shield” that allows tumors to evade immune attack." (PMID 40563367, 2025). "Regulatory T cells, which produce IL-10, contribute to immune suppression within the tumor microenvironment." (PMID 40585643, 2025). "IL-10 is an immunosuppressive cytokine involved in immune regulation, angiogenesis, and significantly influences tumor growth and metastasis by directly affecting both tumor and immune cells." (PMID 41438510, 2025). "Beyond its well-characterized anti-inflammatory properties, IL-10 has also been shown to improve anti-tumor efficacy in the context of CAR-T cell therapy." (PMID 41584600, 2025). "By applying an in-silico multidimensional model integrating spatially resolved and single-cell gene expression data to show that release of IL-10 promotes T cell exhaustion, thereby contributing to the immunosuppressive tumor microenvironment." (PMID 40040705, 2025). "Although cytotoxic CD8+ T-cells can trigger anti-tumor immune responses, their activity is inhibited by regulatory T cells (Tregs) and immunosuppressive cytokines such as IL-10 and TGF-β." (PMID 41307758, 2025). "The ELISA results revealed that the culture supernatant from recombinant virus-treated tumor cells significantly increased IL-6 secretion and decreased IL-10 secretion in BMDMs." (PMID 40082916, 2025). "Factors such as interleukin-10 (IL-10), a cytokine with anti-inflammatory properties, and the release of extracellular vesicles carrying miRNAs and other bioactive molecules from tumor cells can further influence microglial behavior." (PMID 40896358, 2025). "Given the complexity of the OCCC TME, therapeutic strategies that combine ICIs with agents targeting key molecules implicated in tumor aggressiveness such as VEGF, HIF-1α, IL-6, IL-10, PI3K, and HDAC6 show considerable promise." (PMID 41383608, 2025). "This interaction led to the polarization of macrophages into the tumor-promoting M2 phenotype, characterized by increased secretion of IL-10, VEGF, and MMP-9, alongside reduced levels of IL-12 and NO." (PMID 40330466, 2025). "The immunosuppressive factor IL-10, derived from Tregs, plays a crucial role in diminishing anti-tumor immune responses by suppressing the activity of Teffs and APCs." (PMID 40771826, 2025). "Promote the release of extracellular vehicles (EVs), significantly reduce the secretion of the anti - inflammatory cytokine IL-10, and indirectly weaken the pro - tumor effect of IL-10." (PMID 41169397, 2025).
tumor (continued). "Due to their plasticity, TAMs exhibit distinct phenotypes: M1-like TAMs mediate tumoricidal, pro-inflammatory effects, whereas M2-like TAMs promote tumor growth, invasion, angiogenesis, and immune suppression via IL-10, TGF-β, VEGF, and PD-L1." (PMID 40869364, 2025). "On the other hand, Treg cells consume IL-2 and release inhibitory cytokines such as TGF-β and IL-10, leading to T-cell apoptosis and promoting tumor growth." (PMID 40458394, 2025). "The increased expression of IL-10 by immune cells can also result from the release of various factors by tumor cells, creating an immunosuppressive microenvironment." (PMID 40484866, 2025). "Conversely, trained tumor-associated macrophages (TAMs) may adopt an immunosuppressive phenotype, supporting tumor growth by promoting angiogenesis, suppressing T-cell responses, and facilitating metastasis through secretion of regulatory cytokines (IL-10, TGF-β)." (PMID 41236793, 2025). "Among them, interleukins like IL-6, IL-8, and IL-10 play prominent roles in shaping tumor behavior and immune cell activity." (PMID 40563651, 2025). "In EBV-positive HL patients, there is a high presence of regulatory T cells (Treg) and Th2 cells, which secrete immunosuppressive cytokines such as IL-6, IL-8, and IL-10, further weakening the host’s anti-tumor immune response." (PMID 40302035, 2025). "TAMs also suppress anti-tumor immunity via IL-10 and TGF-β, remodel the ECM through matrix metalloproteinases, and induce epithelial-mesenchymal transition, fostering invasion." (PMID 41230456, 2025). "Concurrently, the immune-suppressive microenvironment shaped by this process secretes high levels of IL-10, which suppresses T cell function and antigen presentation, providing a barrier for immune evasion by tumor cells." (PMID 41394847, 2025). "Hypoxic conditions, IL-4, IL-10, and TGF-β collectively promote the differentiation of macrophages into the M2 phenotype, which is closely associated with immunosuppressive and tumor-promoting functions." (PMID 40909271, 2025). "Specifically, recent studies demonstrate that KLRG1+ ILC2s can acquire anti-tumor functions through IL-10 production and IL-33–mediated activation." (PMID 40497988, 2025). "Among these cytokines, IL-10 plays a pro-tumor role through regulating a variety of signaling pathways, including ERK1/2, STAT3 and NF-κB, and regulating the expression of related genes." (PMID 41145470, 2025). "IL-10, a pleiotropic cytokine secreted by regulatory T cells (Tregs), M2 macrophages, and tumor cells, plays a dual role in the tumor microenvironment." (PMID 40510340, 2025). "These polarized macrophages, in turn, act on tumor cells by secreting cytokines such as IL-10, thereby promoting tumor cell proliferation and metastasis." (PMID 41360767, 2025). "Tregs, myeloid-derived suppressor cells (MDSCs), and tumor-associated macrophages (TAMs) contribute to an immunosuppressive milieu by secreting cytokines such as TGF-β and IL-10, which inhibit T cell activation." (PMID 40660400, 2025). "Once monocytes reach the bone marrow, they can be reprogrammed into tumor-associated macrophages (TAMs) with osteoclast-activating properties, leading to CCL2 and IL-10 production and promoting bone resorption." (PMID 41010912, 2025). "This interaction activates the STAT3 signaling pathway, upregulating immunosuppressive molecules such as FOXP3, CD39, and IL‐10, while promoting the recruitment of peripheral Tregs to tumor sites and facilitating the conversion of CD4+ T cells into Tregs." (PMID 41201063, 2025). "Conversely, IL-10 plays a dual role—suppressing excessive inflammation while contributing to tumor immune escape through inhibition of cytotoxic T-cell activity." (PMID 41303495, 2025). "M2d macrophages induce the secretion of IL-10 and vascular endothelial growth factor (VEGF), a phenotype that contributes to tumor mass survival and is thought to be caused by tumor secretion factors." (PMID 41301548, 2025).